GHRH (growth hormone releasing hormone)
Diseases named in the same sentence as GHRH in open-access papers (continued):
Sharing a sentence is not in itself a finding about the gene and the disease.
COVID-19 (1 paper, 2023). A disease caused by infection with severe acute respiratory syndrome coronavirus 2. "However, to date, the antinflammatory role of GHRH antagonists in COVID-19 remains unexplored." (PMID 37649486, 2023). "Overall, these findings demonstrate a novel antinflammatory role for GHRH antagonists of MIA class and suggest their potential development for the treatment of inflammatory diseases, such as COVID-19 and related comorbidities." (PMID 37649486, 2023).
dilated cardiomyopathy (1 paper, 2017). Cardiomyopathy which is characterized by dilation and contractile dysfunction of the left and right ventricles. "Broglio and colleagues were the first to report in a small group of patients with dilated cardiomyopathy (n ≈ 30) an impaired GH response to GHRH alone and combined with arginine." (PMID 28095492, 2017).
experimental autoimmune encephalomyelitis (1 paper, 2018). An autoimmune demyelinating disease of the central nervous system that is produced experimentally in animals by the injection of homogenized brain or spinal cord in Freund's adjuvant. "These mice are less prone to develop experimental autoimmune encephalomyelitis (EAE) and GH supplementation (but not GHRH) restores original susceptibility of EAE." (PMID 30333823, 2018).
fibromyalgia (1 paper, 2021). A chronic disorder of unknown etiology characterized by pain, stiffness, and tenderness in the muscles of neck, shoulders, back, hips, arms, and legs. "Researchers have injected fibromyalgia patients simultaneously with CRH, TRH, GHRH as well as GnRH—however, this was not done in order to assess the therapeutic potential of secretagogues but to study the patients' endocrine dysfunctions." (PMID 34026797, 2021).
gastric ulcer (1 paper, 2019). An ulcerated lesion in the mucosal surface of the stomach. "Moreover, EGF has been found to be involved in the gastric ulcer healing effect of Growth Hormone-Releasing Hormone (GH-RH), as well as exhibits an inhibitory effect on gastric acid secretion in isolated gastric glands." (PMID 30934722, 2019).
glaucoma (1 paper, 2022). Increased pressure in the eyeball due to obstruction of the outflow of aqueous humor. "Genes co-expressed with PTPN5 were correlated with “Retinal ganglion cell damage in glaucoma”, “Development_Transcriptional regulation of megakaryopoiesis”, and “Development_Growth hormone-releasing hormone (GH-RH) signaling”." (PMID 36556168, 2022).
Glucocorticoid deficiency (1 paper, 2025). "Glucocorticoid deficiency causes growth failure by decreasing growth hormone secretion owing to a decreased expression of growth hormone-releasing hormone (GHRH) and growth hormone secretagogue receptors." (PMID 40539145, 2025).
gynecologic cancer (1 paper, 2017). "Our findings also agreed with the results of previous studies suggesting that GHRH antagonist may inhibit cell motility and growth in gynecologic cancer cell lines." (PMID 28032599, 2017).
hypopharyngeal cancer (1 paper, 2025). Carcinoma, predominantly squamous cell, arising from the epithelial cells of the hypopharynx. "For hypopharyngeal cancer, GHRH, UCN3, LCE2B, DDC, and PCDHGC5 were upregulated." (PMID 40255484, 2025).
hypothalamic disorder (1 paper, 2015). Neoplastic, inflammatory, infectious, and other diseases of the hypothalamus. "However, some have questioned the validity of the GHRH + arginine test in those with hypothalamic disorders, given that GHRH is of hypothalamic origin." (PMID 28943608, 2015).
Intrauterine growth restriction (1 paper, 2018). "Intrauterine growth restriction in pigs is associated with an increase in brain dopaminergic activity, which leads in consequence to a reduced somatostatin tonus on growth hormone releasing hormone secretion and therefore to higher GH concentrations at least in men." (PMID 29762475, 2018).
ischemia (1 paper, 2016). A hypoperfusion of the BLOOD through an organ or tissue caused by a PATHOLOGIC CONSTRICTION or obstruction of its BLOOD VESSELS, or an absence of BLOOD CIRCULATION. "Agonists of GHRH applied to the post infarct myocardium improved cardiac remodeling and helped resolve ischemia." (PMID 27774107, 2016). "The recent demonstrations by our group and others, respectively, that JI-38 markedly enhanced the functional properties and potential therapy by MSCs and cardiac stem cells in different models of ischemia raise the possibility that GHRH agonists may be useful agents to augment clinical cell therapy." (PMID 27774107, 2016).
Laron syndrome (1 paper, 2019). Laron syndrome is a congenital disorder characterized by marked short stature associated with normal or high serum growth hormone (GH) and low serum insulin-like growth factor-1 (IGF-I) levels which fail to rise after exogenous GH administration. "Genomic profiling conducted on Laron syndrome patients emphasizes the key role of the GHRH-GH-IGF1 axis in cancer biology." (PMID 31208077, 2019).
lung fibrosis (1 paper, 2019). "PI3K/AKT signaling is involved in the pathogenesis of bleomycin-induced fibrosis, and suppression of the PI3K/AKT pathway by GHRH antagonist could also lessen lung fibrosis." (PMID 31392398, 2019).
mesothelioma (1 paper, 2022). A usually malignant and aggressive neoplasm of the mesothelium which is often associated with exposure to asbestos. "Here, we demonstrate that the GHRH antagonist MIA-690 potentiates the antitumor effects of the chemotherapeutic drugs cisplatin and pemetrexed, in vitro, in mesothelioma cells, and particularly in vivo, in mice PM xenografts." (PMID 36232554, 2022).
pituitary deficiencies (1 paper, 2013). "Two subjects were excluded from this per-protocol analysis: 1 subject had only 2 pituitary deficiencies instead of the 3 required, and another subject did not have 3 hormone deficiencies and a low IGF-I or confirmed AGHD from an arginine+GHRH test and was randomized in error." (PMID 23559086, 2013).
prostate tumors (1 paper, 2016). "A reduction of viability has been described in breast and prostate tumor cells with the antagonist JMR-132 as well as in other cell types with other GHRH antagonists." (PMID 27448980, 2016). "GHRH antagonists, JMR-132 and JV-1-38 inhibit the growth of androgen-independent prostate tumors." (PMID 27448980, 2016).
pulmonary edema (1 paper, 2014). Accumulation of fluid in the lung tissues causing disturbance of the gas exchange that may lead to respiratory failure. "Since GHRH agonists have a longer half-life than the native hypothalamic GHRH hormone, they can provide a more potent signal to damaged lungs and could promote a change in the concept of treating pulmonary edema." (PMID 25076911, 2014).
rectal cancer (1 paper, 2023). A primary or metastatic malignant neoplasm that affects the rectum. "Although GHRH-antagonists have not yet been introduced into the clinical practice, the potential importance of GHRH-R both as a probable molecular target of therapy and—based on our present findings—as a predictor for survival in locally advanced rectal cancer is highly plausible." (PMID 36979698, 2023).
renal cell carcinoma (1 paper, 2025). "Though high-affinity receptors for VIP are also present on CAKI-1 renal cell carcinoma (RCC), it was clearly demonstrated that these receptors do not recognize hGHRH and its analogs and display markedly lower or almost negligible binding to GHRH antagonists such as JV-1-42." (PMID 39934495, 2025).
renal failure (1 paper, 2009). "In this current open label pilot study we have analyzed the impact of the plasmid GHRH/EP approach to treat renal failure and its complications in affected companion animals (dogs and cats) as a model for human disease." (PMID 19149896, 2009). "Here we show that a one-time treatment with a plasmid expressing GHRH followed by EP can improve the outcome of companion animals with renal insufficiency." (PMID 19149896, 2009). "Currently, GHRH, GH or IGF-I or their functional biological equivalents are used as recombinant proteins in the treatment or management of renal failure and impaired growth that is associated with this condition." (PMID 19149896, 2009).
Stillbirth (1 paper, 2024). Death of the fetus in utero after at least 22 weeks of gestation. "In addition, within the GHRH group, the survival rate of offspring increased uniformly, whereas the rate of stillbirths decreased." (PMID 38672296, 2024).
Stroke (1 paper, 2024). Sudden impairment of blood flow to a part of the brain due to occlusion or rupture of an artery to the brain. "Furthermore, it is important to note that the patient had history of stroke, likely contributing to the decline in response during the GHRH/arginine test." (PMID 38819617, 2024).
temporal lobe epilepsy (1 paper, 2017). A localization-related (focal) form of epilepsy characterized by recurrent seizures that arise from foci within the temporal lobe, most commonly from its mesial aspect. "GHRH expression was significantly increased in both patients with temporal lobe epilepsy (TLE) and in two mouse models induced by KA or PTZ compared with that in the normal groups (P < 0.05 or P < 0.01)." (PMID 29273763, 2017).
Thrombocytopenia (1 paper, 2025). A reduction in the number of circulating thrombocytes. "The safety profile of GHRH plasmid therapy is generally favorable, though transient hematological abnormalities were noted in five cases, with two experiencing severe transient thrombocytopenia." (PMID 41030680, 2025).
tongue cancer (1 paper, 2025). A malignant neoplasm affecting the tongue. "The findings revealed that, in comparison to their levels in normal tissues, the genes GAL, GHRH, LCE2B, PCDHGC5, and MT3 were notably upregulated in tongue cancer, while NTS was downregulated." (PMID 40255484, 2025).
TSH resistance (1 paper, 2024). "TSH resistance was described in the totality of the cases (20/20) whereas PTH, GHRH, and LH/FSH resistance were reported in 90%, 69%, and 6% of the cases, respectively." (PMID 39456695, 2024).
tumor (58 papers, 1997 to 2025). "Another palliative approach to tumor-bearing dogs employed gene therapy with gene encoding growth hormone releasing hormone in order to ameliorate tumor cachexia and improve the general clinical status of patients." (PMID 23171444, 2012). "Furthermore, the presence of GHRH-Rs has been shown in primary human tumor cells, representing a target for diagnostic or therapeutic intervention using GHRH analogs." (PMID 39934495, 2025). "Both pGHRH-R and its variants are GPCRs and appear to mediate the effects of GHRH in tumours, where it acts as an autocrine/paracrine growth factor in several types of human cancers and, similarly, IGF-I acts as a potent mitogen for tumour cell growth and proliferation." (PMID 39456984, 2024). "The early development of GHRH peptide antagonists improved upon pharmacokinetic properties, target binding, and anti-tumor effects." (PMID 40427140, 2025). "GHRH antagonists exert their antitumor activity by binding to GHRH-R and SV1, thereby disrupting the autocrine/paracrine mitogenic signaling mediated by tumor-derived GHRH, IGF1, and IGF2." (PMID 40244089, 2025). "The results of the expression of the protumour factor GHRH in PC-3 tumours showed that after treatment with the GHRH-R antagonist and the EGFR inhibitor, there was a decrease in expression." (PMID 39456984, 2024). "For many years, a wide diversity of cancers were known to produce GHRH and express receptors for it, yet only recently was it proposed to function as an autocrine growth factor for neoplasms." (PMID 39417961, 2024). "GHRH antagonists can also suppress tumor growth in a direct manner through blockade of autocrine GHRH action." (PMID 38957466, 2024). "Other studies performed xenografts of CRPC cells in mice and observed a reduction in tumour volume after treatment with different GHRH antagonists of the MIA series." (PMID 39456984, 2024). "Regarding the prognosis of GHRH-secreting tumors (NETs), surgical resection of the primary tumor is the treatment of choice in the majority of cases." (PMID 39449742, 2024). "Antagonistic GHRH analogs were initially designed to block the effects of GHRH on tumor cells, with the hope of exploiting the presence of GHRH receptors in certain cancer types." (PMID 39592529, 2024). "Synthetic GHRH-Ant were then produced in order to develop a class of anti-cancer agents, demonstrating inhibition of human tumor growth in vitro and in vivo against renal, bone, breast, pancreatic, prostatic, colorectal, and lung cancers." (PMID 39417961, 2024). "Signalling mediated by growth hormone-releasing hormone (GHRH) is highly involved in tumour cell progression and metastasis." (PMID 39456984, 2024). "Our findings pave the way for further development of novel, highly potent GHRH peptide analogs for GHRH-R based targeted tumor therapy, as valid alternative options to the current treatment strategies." (PMID 39201517, 2024). "This inhibition of tumor growth was comparable to that observed with the GHRH antagonist MIA-602, suggesting that the agonist paradoxically downregulated GHRH receptors in the tumor microenvironment." (PMID 39592529, 2024). "Although GHRH was first identified in tumor tissues in earlier 1980s, its potential role in carcinogenesis was not extensively explored until the mid-1990s." (PMID 39592529, 2024). "DTX has been employed in a combination therapy with JMR-231, a growth hormone-releasing hormone (GHRH) antagonist, which reduced tumor growth by 71.6% in MDA-MB-231 xenograft mice." (PMID 35440077, 2022). "GHRH tumor secretion can be proved by measuring its plasmatic levels and using histopathological methods with immunohistochemical techniques, however, these are still hardly accessible procedures." (PMID 35757397, 2022). "Considering that GHRH is ectopically expressed, it was suggested that it can act as an autocrine/paracrine growth factor in tumor development." (PMID 36540765, 2022).
tumor (continued). "The stimulatory loop, formed by tumor-derived GHRH and its receptors, can be blocked by GHRH antagonists, resulting in inhibition of tumor growth in experimental models." (PMID 34944669, 2021). "A 5-year-old boy was described with a mammosomatotroph macroadenoma causing gigantism, while another case of MEN1-related gigantism was due to a pancreatic GHRH-secreting tumour." (PMID 33543431, 2021). "This stimulatory loop induced by GHRH can be blocked by GHRH antagonists, leading to the inhibition of tumor growth in experimental models." (PMID 34439107, 2021). "GHRH itself enhances tumor growth, and GHRH-R antagonists inhibit tumor stromal fibrosis in experimental models." (PMID 33096674, 2020). "Treatment with somatostatin analogs can directly inhibit GHRH secretion from tumor cells and lead to a reduction in GHRH, GH and IGF-1 levels." (PMID 31766255, 2019). "Nevertheless, the main inhibitory effect of GHRH antagonists on tumor growth appears to be exerted through GHRH receptors which are present in various human cancers." (PMID 29983893, 2018). "In our studies on GHRH antagonists, we have previously shown an association between the levels of serum or tumoral IGF-1 and tumor growth." (PMID 29983893, 2018). "Because of this, synthetic agonists and antagonists of GHRH have attracted wide attention in recent years as global regulators of cell growth with therapeutic potential including tissue regeneration and tumor suppression, respectively." (PMID 27774107, 2016). "By obstructing the interaction of GHRH with its receptor using an GHRH antagonist, it should be possible to prevent or reduce tumor cell hyperplasia by this pathway." (PMID 27774107, 2016). "Such locally generated GHRH circuits in tumor cells trigger bioactive and immune responses that directly impact tumor cell proliferation and expansion." (PMID 27774107, 2016). "The pGHRH-R and SV1 mediate the stimulatory effects of GHRH and the inhibitory effects of GHRH antagonists on tumor tissues." (PMID 27448980, 2016). "Regulation by GHRH analogues of the proliferation of normal tissues and neoplasms provides for promising approaches to clinical treatments directed at tissue repair and antitumor treatments." (PMID 27774107, 2016). "All these studies confirm the complexity of growth regulation and signaling pathways in tumor cells that expose multiple potential targets for GHRH and its antagonists." (PMID 27774107, 2016). "Molecules known to play important roles in cell proliferation including cAMP, PKC, and p21 have been shown to be the effective inhibited targets of GHRH antagonists for their antiproliferation and tumor suppressive actions." (PMID 27774107, 2016). "Studies on human cancer lines xenografted into nude mice have demonstrated anti-tumor activity of GHRH antagonists against multiple human cancer types." (PMID 25593995, 2014). "In vivo studies have demonstrated the anti-tumor activity of GHRH antagonists against multiple cancer types." (PMID 22941871, 2012). "We conclude that treatment of TNBC with GHRH antagonists reduces tumor growth through an action mediated by tumoral GHRH receptors and produces a suppression of inflammatory cytokine signaling." (PMID 22941871, 2012). "In this study, the human TNBC cell lines, HCC1806 and MX-1, were xenografted into nude mice to evaluate the effects of the GHRH antagonist MIA-602 on tumor growth and inflammatory cytokine gene expression." (PMID 22941871, 2012). "Recently, peptide receptors that mediate the effects of GHRH and its antagonists on tumours were identified." (PMID 18506184, 2008). "The present study demonstrates the tumorigenic effect of GHRH in the human experimental tumour cell lines representative of leading cancers." (PMID 18506184, 2008). "One of these mechanisms is based upon the inhibition of the secretion of autocrine/paracrine IGF-I or IGF-II from the tumours, while probably the most important pathway involves the blockade of action of autocrine GHRH in tumours." (PMID 18506184, 2008).